Y_RNA (Y RNA )
Gene: Miscellaneous RNA gene on chromosome 22 (28,303,754 to 28,303,850, forward strand). Ensembl gene ENSG00000199797.
Homologues: Orthologues: chimpanzee Y_RNA (99% identical). Paralogues in human: Y_RNA (89% identical), Y_RNA (87% identical), Y_RNA (86% identical), RNY3 (85% identical), RNY3P14 (85% identical), Y_RNA (85% identical), RNY3P1 (84% identical), Y_RNA (84% identical), RNY3P11 (82% identical), RNY3P12 (82% identical), RNY3P5 (82% identical), Y_RNA (82% identical), and 90 more.